YAP1 (Yes1 associated transcriptional regulator)
Diseases named in the same sentence as YAP1 in open-access papers (continued):
Sharing a sentence is not in itself a finding about the gene and the disease.
tumor (continued). "In combination with Gαs, FFAR1/2/4 activates PKA-induced phosphorylation of MST1/LATS1; thereafter, YAP1 is phosphorylated and detained in the cytoplasm, which inhibits cell proliferation and cell metastasis, and induces apoptosis of tumor cells 80-82." (PMID 32760212, 2020). "Therapeutic opportunities targeting the YAP1/TEAD-dependent transcription are being tested in different neoplasms." (PMID 32436169, 2020). "Here, we demonstrated miR-590-5p as a tumor suppressor in GC by negatively regulating YAP1, a major downstream effector of the Hippo pathway." (PMID 32066878, 2020). "Our data indicated that resistant tumors are enriched in CSCs and YAP1/BET inhibition by JQ1 significantly suppresses resistant tumor cell growth, tumorsphere formation, and reduced population of CSCs." (PMID 32175692, 2020). "LATS2 is a core kinase component of the Hippo tumor-suppressive signaling pathway that encodes a Ser/Thr protein kinase and LATS2-mediated YAP1 phosphorylation has been implicated in multiple human cancers." (PMID 32041942, 2020). "While YAP1 is elevated, the miR-214-3p is downregulated in tumor species compared to the matched normal bronchial epithelium using q-PCR analysis." (PMID 32863772, 2020). "The significant up-regulation of YAP1 in cancers having a TMPRSS2:ERG fusion is consistent with data showing that ERG can activate YAP1 dependent transcription and tumour development." (PMID 32488048, 2020). "Taken together, these results demonstrated that miR-103a-3p promotes tumour glycolysis by regulating the Hippo/YAP1/HIF1A axis." (PMID 33218358, 2020). "c-Yes activation promotes the growth and tumor formation of β-catenin-active CRC cell lines by promoting the expression of BIRC5 and BCL2L1, the transcriptional targets of the β-catenin/Yes-associated protein 1 (YAP1)/TBX5 complex." (PMID 32456226, 2020). "Mechanistically, PVT1 lncRNA knockdown increased phosphorylated LATS1 and phosphorylation of YAP1 which led to inactivated YAP1 leading to tumor growth inhibition." (PMID 31601234, 2019). "Next, we examined the effects of YAP1 on the regulation of NMU gene expression in tumor cells in vitro." (PMID 31575084, 2019). "Taken together, these results suggested that the mutual regulation of PVT1 and YAP1 exists in EAC cells and simultaneous inhibition of PVT1 and YAP1 lead to more effective suppression of EAC tumor growth than that of either gene alone." (PMID 31601234, 2019). "There are decreased YAP1 mRNA levels in high-grade tumors as compared to low-grade tumor samples, which parallels that of PDEF." (PMID 31835563, 2019). "The Hippo pathway component YAP1 has been shown to bypass K-Ras addiction, and allow tumor growth, in a Ras-null mouse model." (PMID 31100813, 2019). "Dysfunction of these tumor suppressive miRNAs results in YAP1 overexpression and subsequent tumorigenesis." (PMID 30934860, 2019). "In EBV-positive gastric cancer, miR-375, which exerts tumor suppressor function through down-regulating YAP1, TEAD4, and CTGF, was down-regulated." (PMID 32038526, 2019). "As we know, Hippo pathway, especially the dysfunction of YAP1 plays tumor-promoting actions in several human cancers." (PMID 31412903, 2019). "miR-21 significantly inhibited YAP1 protein expression in 786-O cells and tumor tissues isolated from nude mice, and YAP1 attenuated the effect of miR-21 on the viability, apoptosis, and migration of 786-O cells." (PMID 31179326, 2019). "Hippo-YAP1 signaling is essential for tumorigenesis and tumor progression in both epidermal and dermal cells." (PMID 31543507, 2019). "YAP1 has been shown as an essential sensor and responder between tumor cells and their microenvironment." (PMID 30934860, 2019). "Of note, NFI and TEAD-binding sites remained the top enriched motifs when we restricted enrichment analyses to YAP1-bound regulatory elements, suggesting that these DNA-binding TFs to be of central relevance for ST-EPN-YAP1 tumor cells." (PMID 31477715, 2019).
tumor (continued). "CCN1/CYR61 is also noted as a famous downstream target of YAP1 in cancers, contributing to tumor growth." (PMID 30934860, 2019). "The cross-linked collagen fibers increase the stiffness and rigidity of tumor that directly participates in the integrin signaling and activation of other oncogenic molecules, including YAP1." (PMID 30899415, 2019). "Some authors have proposed that YAP1 dysregulation promotes tumor development through a p38 regulation of cAMP response element-binning (CREB) transcription factor." (PMID 31717606, 2019). "This oncogenic function of YAP1 is further supported by tumor suppressors such as Mst1/2 and Sav1 which inhibit YAP1 activity by phosphorylation." (PMID 31731480, 2019). "This study aimed to prove that YAP1 plays a tumor‐promoting role in Hp‐induced gastric carcinogenesis via activating the key cancer‐related inflammatory cytokine IL‐1β and thereby provide a new drug target for GC treatment." (PMID 31145543, 2019). "Taken together, our data indicate that YAP1 drives P4HA2 expression in RASSF1A‐methylated tumours, resulting in increased organization of collagen and elevated stiffness of the tumour microenvironment." (PMID 31268606, 2019). "Here the authors show that a YAP1- MAMLD1 fusion drives tumor formation in mice and show that the fusion protein can collaborate with the TEAD and NFI transcription factors." (PMID 31477715, 2019). "Recent studies have also shown that YAP1 contributes to the establishment of an immunosuppressive tumor microenvironment." (PMID 31137841, 2019). "The final xenograft tumor weights in the YAP1‐silenced groups were significantly lower than that in the control groups." (PMID 30868052, 2019). "In this study, we demonstrate that Hp promotes tumor‐accelerating inflammation by enhancing YAP1 expression and nuclear translocation." (PMID 31145543, 2019). "YAP1 is highly expressed in both human and mouse OS and knockdown of YAP1 was found to reduce OS tumor progression in mouse models." (PMID 31836741, 2019). "In vitro studies for other types of YAP-driven cancers have proposed reduction of YAP1 dosage effects to induce tumor regression." (PMID 31477715, 2019). "And Immunohistochemistry (IHC) assay was performed to assess the expressions of CCNE1/2 and Yap1 proteins in the tumor tissues from the model." (PMID 31455378, 2019). "We found that overexpression of YAP1 partially reversed the tumor-inhibiting effect CLDN6 knockdown." (PMID 31827075, 2019). "The growth of tumor is substantially suppressed by YAP1-knockdown, shown as the tumor volume and tumor weight are reduced in YAP1-knockdown group." (PMID 31175271, 2019). "Apart from the fundamental role of Hippo signaling in development and tumor growth, increasing studies indicate the nuclear YAP1 serves as an effective sensor and responder for mechanical stimulus." (PMID 30934860, 2019). "Tumor cells in experimental OPA had strong nuclear labeling for total YAP1, but this appeared to be less intense in natural OPA." (PMID 31434729, 2019). "IHC staining of harvested tumor tissues from the LLC model further confirmed the reduction of YAP1 levels from DGUOK depletion." (PMID 31633874, 2019). "Using patient-derived xenograft mice models in which the heterogeneity of the primary human tumor was preserved, we found that simultaneous blockade of YAP1 and STAT3 by verteporfin suppressed CSC activity and tumor growth when combined with chemotherapy." (PMID 31137841, 2019). "Consistent with this, IHC analysis confirmed the presence of nuclear YAP1 in OPA tumor cells, suggesting a possible role for Hippo signaling in OPA pathogenesis." (PMID 31434729, 2019). "Immunostaining with an anti-YAP1 antibody revealed predominant nuclear expression of the YAP1 protein in tumor cells." (PMID 31477715, 2019). "Recent data has indicated that MZF1 is essential for the transcription of basal YAP1, and promotes tumor formation through stimulating the expression of YAP1." (PMID 30961610, 2019).
tumor (continued). "It is reported that miR-375 exerts tumor suppressor function in GC through down-regulating the expression of three components of the Hippo pathway, YAP1, TEAD4, and CTGF." (PMID 32038526, 2019). "This interaction data is consistent with the comparative transcriptome profiles analysis between ST-EPN-YAP1 and ST-EPN-RELA subgroups, which showed that these genes are YAP1-specific in both our mouse model and human tumor samples." (PMID 31477715, 2019). "Relapsed tumors retain KRAS* pathway suppression and a subset harbor genomic amplification of the Hippo pathway transcriptional coactivator, YAP1, which we have confirmed in 3 of 7 ‘Escaper’ tumor cells lines (cell lines denoted as EY1-3)." (PMID 31134896, 2019). "To confirm the association between YAP1-modulated NMU expression and tumor incidence and metastasis, we constructed stable Y-2SA cell lines transfected with shRNA against NMU (Y-2SA-shNMU)." (PMID 31575084, 2019). "In naïve T-cell, YAP1 promotes polarization to regulatory T-cell through inducing TGFBR2 for immunosuppressive tumor microenvironment." (PMID 31137841, 2019). "While amplification of wildtype YAP1 is involved in tumor formation in various mammalian tissues, we recently identified unique YAP1 fusion variants as a characteristic hallmark of the human ST-EPN group, ST-EPN-YAP14,8." (PMID 31477715, 2019). "This is also in agreement with the reported correlation of high nuclear YAP1 expression with poor patient outcome and tumor stage of CRC." (PMID 31717606, 2019). "Utilizing the NeuroD2:SmoA1 mouse model, we performed electroporation of tumor slices with plasmid DNA for either a scrambled shRNA or two separate YAP1 shRNAs." (PMID 31541170, 2019). "In CRC, a study has suggested that the combination of YAP1 inhibitors with cetuximab can inhibit DDX3-mediated tumor aggressiveness and sensitize CRC to cetuximab." (PMID 31543507, 2019). "The emerging picture from relevant experimental and clinical data suggests that oncogenic KRAS, YAP1 and β -catenin serve similar roles in cell cycle control in tumor initiation." (PMID 30961610, 2019). "Activated SRC drives YAP1 to transfer into the nucleus of the basal layer cells thus to activate the transcription of genes for regenerating or tumor progression." (PMID 30934860, 2019). "Multiple miRNAs have been reported to be involved in GC as tumor suppressors and some of them directly target YAP1." (PMID 30934860, 2019). "Overall, our oncogenomic and functional analyses support the role of FAT1 in cancer as a tumor suppressor acting upstream of YAP1." (PMID 29985391, 2018). "Since Reactome “YAP1 and TAZ stimulated gene expression” gains cePathway relationships with several tumor-associated growth factor pathways (e.g. EGFR, TGFβ and IGF), YAP and TAZ would promote the growth factor pathways possibly through ceRNA relationships." (PMID 29565967, 2018). "NF2 alteration leads to the activation of the transcription factor YAP1 and the expression of multiple downstream targets promoting tumor cell survival and proliferation." (PMID 29535838, 2018). "We then examined YAP1 or CTGF protein expression correlation with miR-375 in 28 frozen primary tumor samples." (PMID 29367737, 2018). "Our current study supports that YAP1 and Slug levels are significantly higher in patient tumor specimens than in adjacent tissues." (PMID 29700328, 2018). "MLN4924, a NEDD8-activating enzyme (NAE) inhibitor, has been shown to suppress CRL4DCAF1 and attenuate YAP1 activation in NF2-mutant tumor cells." (PMID 29565815, 2018). "YAP1 immunoreactivity was found in the nuclei of tumor cells in 64.8% of ccRCC patients, whereas only 24.1% of tumors revealed cytoplasmic YAP1 expression." (PMID 29850494, 2018). "In both cases, VP reduced tumor growth and cancer cell proliferation when administered daily, suggesting that YAP1 is an attractive therapeutic target in human HNSCC and likely other human malignancies." (PMID 29985391, 2018).
tumor (continued). "In our previous study we found at both mRNA and protein levels that LATS1 gene expression was downregulated and YAP1 expression upregulated in ccRCC tumor tissues in comparison to corresponding samples of unaltered kidney tissues." (PMID 29850494, 2018). "circFAT1 knockdown reduced the mean area immunopositive for YAP1, c-Myc, and Birc5 in tumor tissues, as determined by immunohistochemistry, this corresponded to a decrease in the levels of YAP1, c-Myc, and Birc5 protein and mRNA." (PMID 30514309, 2018). "Direct evidence from our laboratory suggests that YAP1 endows self-renewal capacity to non tumorgenic cells and tumor cells in EAC." (PMID 30234141, 2018). "In particular, Slug expression levels were much higher in tumor tissues than in adjacent tissues; YAP1 was also highly expressed in tumor tissues." (PMID 29700328, 2018). "miRNAs with tumor-suppressive function, especially miR-375, also play a crucial role in the activation of YAP1/TEADs-CTGF cascade." (PMID 29367737, 2018). "In comparison to the respective cellular compartments of PCT cells of normal kidney the immunoexpression of YAP1 was significantly increased in the nuclei and decreased in the cytoplasm of ccRCC tumor cells." (PMID 29850494, 2018). "Three weeks after tumor cell injection, tumors with diminished YAP1 expression exhibited a substantially smaller volume and lower weight." (PMID 29163769, 2017). "Next, we expanded our analysis to additional tumours from these mice, focusing on expression changes and potential genomic amplifications of the Yap1, Met and Akt3 genes." (PMID 28194015, 2017). "Oropharyngeal tissue was collected from CO2 laser resections, and probed with YAP1 antibody in tumor and pre-malignant regions of HPV positive OPSCC tissue." (PMID 28222762, 2017). "Immunohistochemistry (IHC) staining of HN137 primary and metastatic tumour tissue revealed small YAP1-high subpopulations within the HN137 primary tumour." (PMID 28874669, 2017). "The Hippo pathway regulates organ size, growth and comprises several tumor related factors, including the oncoprotein YAP1 and the tumor suppressor RASSF1A." (PMID 29179447, 2017). "YAP1-silencing led to the concomitant decreased expression of major oncogenic pathways including Kras, mTOR, β-catenin, and M2-promoting IL-4 and tumor-promoting IL-6 cytokines." (PMID 28241877, 2017). "Here we revealed that re-expression of RASSF1A promotes its tumor suppressive function through the activation of pro-apoptotic and anti-proliferative YAP1 target genes (e.g. BAX and CDNK1A) in TREx293 cells." (PMID 29179447, 2017). "Knocking out nuclear YAP1 can inhibit tumor cell proliferation, while increased expression of YAP1 can promote cell growth and migration and inhibit apoptosis." (PMID 28533948, 2017). "YAP1, an effector of the Hippo signaling pathway, has been reported as an oncogene in several tumor types." (PMID 29312609, 2017). "Studies have demonstrated that Sox2 can enhance the function of YAP1 thus maintain the stemness of tumor cells." (PMID 29296212, 2017). "YAP1, a key downstream effector of Hippo tumor suppressor signaling pathway, regulates multiple cellular processes by activating several transcription factors, such as TEAD1-4, and has been suggested to be a candidate human oncogene in multiple tumors." (PMID 28915618, 2017). "Although YAP1 behaves as an oncogene in several cancers, recent data suggest that YAP1 also has tumor suppressor functions in some contexts." (PMID 29228705, 2017). "YAP1 overexpression also contributes to self-renewal and tumor-initiation capacities in cancer stem cells." (PMID 27911857, 2017). "These factors were then subjected to multivariate Cox regression analysis, which indicated that depth of invasion (P = 0.014), tumor size (P = 0.010) and nuclear YAP1 expression (P = 0.000) were independent prognostic factors." (PMID 29113304, 2017).
tumor (continued). "Previous reports have suggested that the tumor suppressive potential of YAP1 is due to its binding to TP73 and its regulation by RASSF1A leading to the expression of pro-apoptotic genes like BBC3/PUMA and BAX." (PMID 29179447, 2017). "Tumor growth increased dramatically in mice injected with YAP1-overexpressing K1 cells compared with those injected with control cells." (PMID 28036290, 2017). "Equally important, the number of CD133+ cells were significantly increased in both YAP1-overexpressing DLD-1 and HCT116 cells; the tumor sphere-forming ability was also markedly enhanced in YAP1-overexpressing cells." (PMID 28241877, 2017). "Although parental and CD133low LNCP cells exhibited reduced capacity to generate tumors, YAP1 transfected CD133low LNCAP cells clearly showed increased tumor forming capacity." (PMID 29383141, 2017). "Hippo-YAP1 is a tumor-suppressor signaling pathway that inhibits cell proliferation and accelerates apoptosis." (PMID 29113304, 2017). "In summary, we observed that RASSF1A promotes its tumor suppressive effect through activation of pro-apoptotic and anti-proliferative YAP1 target genes." (PMID 29179447, 2017). "We further detected the expression of six candidates in CCA patients; YAP1 was confimed as the most significant upregulatd target genes in the tumor tissues of CCA patients." (PMID 28915618, 2017). "Recently YAP1 has been reported to play a role as a tumor suppressor during intestinal regeneration in human colorectal cancer." (PMID 28645247, 2017). "YAP1-positive staining was confined primarily to the cytoplasm and nuclei of tumor cells, while HSPC111-positive staining was confined mainly to the cytoplasm of tumor cells." (PMID 29113304, 2017). "In agreement with our in vitro data, +TAM tumor sample showed an increased level of YAP1, Kras, Akt/mTOR, NF-kB (oncogenic markers), and β-catenin (both oncogenic and stemness marker)." (PMID 28241877, 2017). "Primary tumours expressed YAP1 in 5–10% of cells that comprised the tumour; whereas, 10% as lowest and up to 90% of the tumour cells in the lymph nodes expressed YAP1." (PMID 28098159, 2017). "In this light, our data suggest that YAP1 and GATA3 are important target genes for future analysis on the impact of SMYD3‐mediated regulation of tumor‐associated genes." (PMID 28781952, 2017). "We next looked for differential protein expression of INSM1 and YAP1 in SCLC tumors by IHC using a discovery TMA containing 22 patient tumor specimens." (PMID 29088741, 2017). "Further, aberrant activation of YAP1 signaling has been demonstrated to promote tumor growth, progression, and metastasis in many solid tumors." (PMID 29228705, 2017). "Although most studies indicate YAP1 acts as an oncogene in different types of cancers, data also suggest that YAP1 has tumor suppressor functions in certain contexts." (PMID 29163769, 2017). "Tumor-associated macrophages can secret EGF to the microenvironment that promotes tumor growth, can play an important role in the regulation of YAP1 expression." (PMID 29163769, 2017). "It has previously been shown that YAP1 affects the stemness of tumor cells and promotes tumor metastasis." (PMID 29296212, 2017). "Our investigation has provided evidence that YAP1 expression is elevated in human PTC tumor tissues and K1 cells." (PMID 28036290, 2017). "In contrast, more than 70% of tumor cells in metastatic tumor nodules showed primarily nuclear YAP1 protein expression." (PMID 28827520, 2017). "Our data also revealed that nuclear YAP1 expression was closely correlated with poor prognosis, lymph node metastasis, clinical stage, and tumor size, suggesting that positive expression of YAP1 was an indicator of highly malignant GC." (PMID 29113304, 2017). "Our results demonstrated that miR-195-5p was a potent suppressor of YAP1, and miR-195-5p-mediated downregulation of YAP1 significantly reduced tumor development in a mouse CRC xenograft model." (PMID 28356122, 2017).